EGFR (epidermal growth factor receptor)
Diseases named in the same sentence as EGFR in open-access papers (continued):
Sharing a sentence is not in itself a finding about the gene and the disease.
tumor (continued). "The results showed that tumor tissues from EGFR TKI-resistant patients had significantly increased GLI1, SMO, BCL2, and SNAIL protein levels compared with those from TKI-sensitive cases, suggesting that these proteins are possibly related to TKI resistance in NSCLC." (PMID 35154464, 2022). "Additionally, they looked at circulating tumor cells (CTCs) and found that there was a high co-expression of EGFR and HER3." (PMID 36551663, 2022). "The tumor-targeting analysis confirmed both EGFR and CD47 are good targets of TNBC." (PMID 35057042, 2022). "Compared with tumor size, the transition time of STMs and EGFR came earlier." (PMID 35543090, 2022). "Likewise, we looked into HPV-positive HNSCC tumours with different grades in the TCGA and found that higher grade tumours appeared to have higher expression of BRD4, CDKNA2, RAD51AP1 and CDC6 with EGFR expression was lesser in higher tumour grades." (PMID 36333293, 2022). "In summary, our findings shed more light on the impact of targeted therapy on the TME, as well as improve our understanding of how the immune cell infiltrate is altered upon continuous long-term exposure to TKI treatment and simultaneous administration of TKIs and ICB in EGFR-driven tumours." (PMID 36010935, 2022). "Targeting atypical PKC decreases tumor growth in EGFR inhibitor-resistant mouse models of GBM." (PMID 35785151, 2022). "Additionally, TNF-α promotes a rapid metalloproteinase-mediated TGF-α shedding from keratinocyte membrane, attributed to EGFR trans-activation and accelerated epithelial cell regeneration (epidermal hyperplasia), which aggravates skin inflammatory conditions." (PMID 36204219, 2022). "Generally, immuno‐based microfluidic and microarray technologies have utilised tetraspanins (CD9, CD81 and CD63) and tumour‐cell surface associated markers such as EpCAM, CA125, CD19, EGFR, EGFRvIII, podoplanin and PDGFR for on‐chip capture of tumour‐EV sub‐populations." (PMID 36239734, 2022). "Thus, to screen for potential chemokine effects on the oncogenic pathway in EGFR-mutant tumor cells, we cocultured tumor cells with activated PBMCs during EGFR-TKI treatment." (PMID 36612121, 2022). "This can lead to skewed results if the expression level of mutated or non-mutated EGFR is not equal between cell lines and can be one of the reasons why a difference in tumor uptake is not observed." (PMID 35455447, 2022). "Besides, MiR-7 can target p21-activated kinase 1, epidermal growth factor receptor, and insulin receptor substrate 1 to influence biological processes like proliferation, migration, apoptosis, and cell cycle of tumor cells in CRC by targeting." (PMID 36199554, 2022). "Other alterations in genes such as EGFR (mutations or amplification) in H3K27M mutants or EZHIP (overexpression) in H3 wild-type midline tumors have also been identified and contributed to the most recent definition of the DMG-H3K27 tumor subtype." (PMID 36568177, 2022). "Conventional identification of EGFR or PD-L1 status requires surgical or biopsied tumor specimens, which are obtained through invasive procedures associated with risk of morbidities and may be unavailable to access tissue samples." (PMID 35250988, 2022). "Moreover, compared to monotherapies, this combination demonstrated more effective cytolytic ability in MDA‐MB‐231 tumour cells and longer lifespan of mice intracranially pre‐inoculated with EGFR‐expressing MDA‐MB‐231 cells." (PMID 35762299, 2022). "The effect of palmitoylation on tumorigenesis is mostly through the modification of key molecules (EGFR, RAS, etc.)of tumor proliferation, death resistance, and tumor metastasis, causing abnormalities in signaling pathways, metabolism, and gene expression regulation." (PMID 35606353, 2022). "EGFR and Her2 are also identified as a biomarker on the surface of circulating tumor cells." (PMID 35428350, 2022). "Furthermore, the Two-in-One antibody demonstrates specific cellular binding properties on EGFR/PD-L1 double positive tumor cells." (PMID 35479092, 2022).
tumor (continued). "The other cluster with lower stage and more differentiated tumor grade and negative EGFR expression represent patients at low risk of distant metastasis." (PMID 36188649, 2022). "Consequently, small molecule inhibitors targeting EGFR have evolved as an attractive strategy to control the tumor growth and treatment of some types of cancers." (PMID 35408693, 2022). "Amplification of PDGFA gene and EGFR gene was detected in 7 tumor foci." (PMID 34987659, 2022). "The epidermal growth factor receptor (EGFR) is another valuable target site for tumours." (PMID 35593206, 2022). "Exome sequencing data were used to estimate tumor purity and detect EGFR amplification." (PMID 36130485, 2022). "Epidermal growth factor receptor (EGFR), the receptor for members of the epidermal growth factor family, regulates cell proliferation and signal transduction; moreover, EGFR is related to the inhibition of tumor cell proliferation, angiogenesis, invasion, metastasis, and apoptosis." (PMID 35840984, 2022). "Recently, EGFR has been identified as a driver of oncogenes in NSCLC, because the mutation of activating EGFR kinase domain enhances the activity of EGFR tyrosine kinase, leading to continuous activation of the downstream signal pathway, and then drives tumorigenesis and tumor progression." (PMID 35515138, 2022). "Moreover, Ce6 was released from Ce6/GE11-(pH) micelles in tumor environments and lysosomes after EGFR-mediated endocytosis, leading to improved elimination of cancer cells in PDT." (PMID 35213974, 2022). "EGFR tyrosine kinase inhibitors (EGFR-TKIs) treatment, demonstrating superior progression-free survival, higher tumor response rates and a better quality of life, are now recommended as the primary therapy for advanced-stage NSCLC patients with EGFR-activating mutations." (PMID 36232650, 2022). "Among non-small-cell lung cancer (NSCLC) patients that are non-smokers, 15-50% have EGFR mutations and 15-25% have K-Ras mutations, both of which play an important role in tumor progression and metastasis." (PMID 35668076, 2022). "Further understanding of the diversity of tumour cells with EGFR statuses may improve the clinical treatment." (PMID 36336787, 2022). "However, in TNBC, although it is a tumor characterized by relatively high rate of EGFR overexpression EGFR, targeted therapy has poor performance." (PMID 35163586, 2022). "Among cells in the tumor microenvironment, bone-marrow-derived mesenchymal stem cells (MSCs), adult multipotent stromal cells with self-renewal and differentiation ability, were found to express a functional EGFR." (PMID 35406622, 2022). "Furthermore, the existence of different forms of aberrant EGFR leads to a heterogenous expression pattern and, therefore, heterogenous signaling abilities, making this tumor entity even more difficult to target with specific therapeutic approaches." (PMID 35486213, 2022). "Epidermal growth factor receptor (EGFR) is a tyrosine kinase transmembrane protein expressed in healthy tissue such as the gastrointestinal tract, epithelial tissues, skin, and hair follicles, and it is also involved in tumor proliferation." (PMID 36358726, 2022). "Furthermore, its expression exhibits strong positive correlations with tumor markers, such as epidermal growth factor receptor (EGFR) and p38 mitogen-activated protein kinases (MAPK)." (PMID 36230880, 2022).
tumor (continued). "Although SLC25A21, EGFR, and COL1A2 are linked to tumour-associated signalling pathways, the precise mechanisms of this synergy remain unclear." (PMID 36246603, 2022). "Moreover, it is known a direct action of NRF2 on proteins involved in chemoresistance such as AKR1C1-3, ABCF2, SLC40A1, as well as on the modulation of important growth factor receptors, such as c-MET, ErbB2 and EGFR regulating tumour growth." (PMID 35453348, 2022). "Among available tumor samples, a higher proportion of tumors without EGFR mutations had positive PD-L1 expression (TPS≥1) and strong positive PD-L1 expression (TPS≥50)." (PMID 35265073, 2022). "Given that in the current clinical routine the decision for targeted therapy, e.g., the use of anti-EGFR antibodies, is commonly based on the RAS-mutational status of a single tumor biopsy, inter-metastatic heterogeneity is likely to greatly influence the treatment outcomes of CRLM." (PMID 35565214, 2022). "Since exosomes are involved in cell-cell communication that alters the phenotype of the recipient/target cells, Exosomal-EGFR expressed by various tumor types may play an important role in cancer progression." (PMID 36114463, 2022). "EGFR may play anti-autophagic role to affect tumor progression and chemoresistance by mediating Beclin 1 phosphorylation." (PMID 35739532, 2022). "Two short peptides intended for EGFR targeting of tumor cells have been described in the prior art." (PMID 36456600, 2022). "We consistently found a clear biotinylation labeling of these cell entities in tissue sections, and confocal microscopy of tumor SCSs could confirm distinct surface biotinylation of CD45+, CD68+, CD31+, and EGFR+ tumor cells." (PMID 35217608, 2022). "Furthermore, to model CAR-T cell-induced lysis of heterogenous populations of tumor cells, we mixed EGFR-expressing tumor cells with CD38-expressing tumor cells." (PMID 36531912, 2022). "Furthermore, previous studies have observed that activation of the EGFR pathway also increases the synthesis of angiogenic molecules in different types of tumour cells." (PMID 35120511, 2022). "Two separate studies found that combining the EGFR inhibitor afatinib with ionizing radiation led to a significant decrease in CSC populations as well as colony forming abilities of these CSCs with an overall decrease in tumor size." (PMID 35409179, 2022). "Notably, the EGFR/STAP-2 interaction is essential for sustaining EGFR expression on the surface of tumor cells by inhibiting the c-CBL-mediated ubiquitination of EGFR." (PMID 36551835, 2022). "On the other hand, PET imaging biomarkers could very well become qualified as predictive biomarkers to predict tumor sensitivity to EGFR TKI." (PMID 36313723, 2022). "It is possible that PD-induced reduction in IL-10 in the tumor microenvironment could affect indirectly EGFR, thus preventing downstream activation of Akt and ERK1/2 kinases in malignant cells." (PMID 35955576, 2022). "Alterations in HER2 and MET could be a target for anti-tumor drugs or lead to resistance to anti-EGFR therapeutics." (PMID 35326608, 2022). "During tumor treatment, the activity of EGFR relevant signal pathways keeps changing." (PMID 35105871, 2022). "The main elements which define the variability in the TME includes but are not limited to genomic instability, tumor type, tumor location, presence of mutations such as KRAS, EGFR, PTEN etc., presence of lymph nodes, adipose tissue in the vicinity, and therapeutic interventions." (PMID 36253762, 2022).
tumor (continued). "However, long-term EGFR-TKI treatment leads to the transformation of tumor immunosurveillance into tumor-promoting inflammation through the induction of Tregs, inhibition of DCs, and the polarization of macrophages toward the M2 phenotype." (PMID 35372081, 2022). "Moreover, due to the comparatively low affinity of HCP-LCE to EGFR (236 nM), increased EGFR cell expression, which is predominantly found on tumor cells, is required for targeting of the antibody." (PMID 35479092, 2022). "Besides, CB1 silencing promoted tumor cell proliferation and M2 polarization which was counteracted by EGFR knockdown." (PMID 35641479, 2022). "For example, stromal-derived factor 1 (SDF-1/CXCL12) secreted by CAFs promotes bone metastasis by interacting with cancer cells through CXCR4, while CAFs-secreted epidermal growth factor receptor (EGFR) can promote bone metastasis by directly interacting with tumor cells." (PMID 36237303, 2022). "Together, these data revealed common features of GBM, including gain of chr.7 and loss of chr.10, lacking IDH1/2 mutations, high frequency of TERT promoter mutation, loss of critical tumor suppressors (e.g., PTEN and CDKN2A/CDKN2B), high frequency of PDGFA and EGFR amplification." (PMID 34987659, 2022). "Patients with concurrent EGFR mutations in pretreatment plasma have shorter PFS (HR = 2.00, 95% confidence interval [CI]: 1.73–2.31, p < .001) and OS time (HR = 2.31, 95% CI: 1.89–2.83, p < .001) compared to the tumor‐only mutation cases." (PMID 34427045, 2022). "In vitro anti-EGFR nanobodies suppressed tumour cell proliferation and growth." (PMID 36071488, 2022). "In the HCC context, EGFR activity was found to have a role in sorafenib resistance, suggesting that EGFR inhibition may increase tumor response to sorafenib." (PMID 36080304, 2022). "In the case of HuCC-A1 cells, no other major oncogenic alteration was detected in addition to the EGFR copy number gain, so it might be assumed to play an essential role in the tumor biology in this case." (PMID 36013219, 2022). "Also, in IDH wild-type glioblastomas, tumor clusters were found to be associated with oncogenic alterations like CDKN2A/B deletion and EGFR amplification." (PMID 36253762, 2022). "Thus, LL-37 expression significantly promotes tumor growth and upregulates the EGFR/HER2/Akt signals in the PLC/PRF-5 xenograft tumor." (PMID 35039485, 2022). "No significant decrease in [18F]MPG tumor uptake was observed in patients with EGFR activating mutations after TKI treatment." (PMID 35455447, 2022). "Thus, treatment efficacy becomes primarily dictated by the specificity of the TPMIL construct for tumor tissue EGFR." (PMID 35748165, 2022). "Several case reports on patients with advanced stage undergoing EGFR-TKI therapy in a neoadjuvant setting suggest that the tumor could be downstaged by the TKI treatment." (PMID 35681639, 2022). "Hence, selective detection of the activity of EGFR-related signal pathways can help to understand the progression of tumor development." (PMID 35105871, 2022). "In addition, Gefitinib (an EGFR-tyrosine kinase inhibitor) is among the anti-tumor drugs involved in the inhibition of the EMT process in tumor cells, with good results in clinical studies so far." (PMID 36499337, 2022). "PET images capture the molecular tumor phenotypes indicating somatic mutations; thus, there is increasing interest in whether PET/CT can predict EGFR mutation status in NSCLC patients to develop individualized treatment." (PMID 36276079, 2022). "In its turn, MICALL1 inhibits tumor growth through EGFR degradation." (PMID 36354672, 2022). "In other words, EGFR-specific antibodies result in disruption of the receptor’s function, suppression of tumor development, and ultimately, Fc signaling by innate immune cells to destroy tumor cells." (PMID 36276117, 2022).
tumor (continued). "Thus, at the individual patient level, across multiple cases, RBM10 inactivation was associated with decreased initial EGFR TKI sensitivity, relatively early clinical progression, and a decreased pathological tumor response in EGFR-mutant LA." (PMID 35579943, 2022). "When tumor-bearing mice were treated with durvalumab alone, it did not suppress tumor growth compared with isotype control, which closely mimicked the limited therapeutic effect of anti–PD-1 and anti–PD-L1 antibodies on EGFR-mutated NSCLC." (PMID 35132961, 2022). "The invasion in the close proximity of the tumor (liver, visceral, or parietal pleura, etc.)was associated with KRAS Q61, OR = 2.177 (95% CI = [0.557, 7.933]); RR2 = 1.656 (95% CI = [1.295, 2.015]); and EGFR mutation RR2 = 1.678 (95% CI = [1.563, 1.791])." (PMID 35681771, 2022). "Deletion of T790M may result from third-generation EGFR-TKI treatment or may be one of the reasons for drug resistance related to tumor heterogeneity." (PMID 35840984, 2022). "In addition, some traditional prognostic factors were also analyzed, and those results displayed a significant correlation between tumor metastasis and high expression of the EGFR (p = 0.0057)." (PMID 36291859, 2022). "Yet, some NSCLC patients whose tumors are harboring EGFR mutations do respond to ICIs and studies have continued to focused on the tumor immune phenotype or somatic mutation features to develop novel and more effective treatments for this population." (PMID 36505399, 2022). "Up to 90% of cancer patients treated with EGFR inhibitors have skin adverse reactions." (PMID 35223483, 2022). "There are several receptors that may be associated with tumor-promoting functions of hCAP18/LL-37, such as FPR2, EGFR, and IGFR1 receptor." (PMID 35039485, 2022). "In the SW48 (WT-EGFR) xenograft model, tumor growth was significantly suppressed in the Ctx-VY, Ctx-Y104D, Ctx-W52D and cetuximab groups compared to the PBS group, and the in vivo antitumor activities of the cetuximab variants were consistent with their binding affinities for EGFR." (PMID 35907884, 2022). "Features from each subregion were selected with least absolute shrinkage and selection operator (LASSO) to build logistic regression models (LRs) for predicting primary tumor types (LR-NSCLC for the NSCLC origin and LR-BC for the BC origin), EGFR mutation status (LR-EGFR) and HER2 status (LR-HER2)." (PMID 35991287, 2022). "For example, afatinib, gefitinib, and sunitinib are EGFR inhibitors, which have been confirmed by many clinical trials, which can significantly inhibit the growth, metastasis and angiogenesis of various cancers, and increase the apoptosis of tumor cells." (PMID 35493077, 2022). "Furthermore, further studies are needed to investigate how the oncogenic signaling of CXCL10 affects the development of long-term resistance in persistent tumor cells that survive immediately after EGFR-TKI treatment." (PMID 36612121, 2022). "EGFR is mostly overexpressed and has been correlated with aggressive forms of tumor cells." (PMID 36114463, 2022). "By contrast, EGFR under expression has been reported with tumor progression." (PMID 35456461, 2022). "For example, over-phosphorylation of EGFR in tumor cells cultured in suspension was observed." (PMID 35428350, 2022). "This suggests that EGFR-blockade may to a larger extent inhibit both tumor growth and dissemination in sensitive models whereas the effects on tumor growth and dissemination seem to be uncoupled from each other in Paclitaxel treated models." (PMID 35139880, 2022). "It was thereby supposed that EGFR expression in ECs of tumor vessels could derive from exosomes released by malignant cells." (PMID 35454874, 2022). "In addition, the average weight and volume (size) of xenograft TNBC tumours in mouse models treated with EGFR‐CAR‐ NK cells were significantly reduced, indicating that the cells inhibited tumour growth in vivo." (PMID 35762299, 2022).